AKR1C1 (aldo-keto reductase family 1 member C1)
Diseases named in the same sentence as AKR1C1 in open-access papers (continued):
Sharing a sentence is not in itself a finding about the gene and the disease.
cervical carcinoma (7 papers, 2013 to 2025). A carcinoma arising from either the exocervical squamous epithelium or the endocervical glandular epithelium. "Multiple studies have revealed that AKR1C1 is upregulated in various cancers, such as lung, breast and cervical cancers, and is associated with cancer metastasis and chemotherapy resistance." (PMID 35967424, 2022). "Likewise, AKR1C1 is overexpressed in cervical cancer (CC) tissues and is linked to the clinical characteristics of CC patients." (PMID 39964621, 2025). "AKR1C1 is also reported to be upregulated in various cancers such as lung, breast, gastric, prostate, and cervical cancers." (PMID 39478199, 2025).
colorectal cancer (6 papers, 2012 to 2025). A primary or metastatic malignant neoplasm that affects the colon or rectum. "CDKN2A and AKR1C1 were established as novel ferroptosis-related signatures that could effectively predict colorectal cancer prognosis." (PMID 36275721, 2022). "There was a significant difference in the expression distribution of TFAP2C, SLC39A8, and AKR1C1 genes between the cetuximab responders and non-responders in colorectal cancer (P < 0.05)." (PMID 34249766, 2021). "We used colorectal cancer (CRC) cell lines and surgical specimens to investigate the methylation status of the KEAP1 promoter region as well as expression of Nrf2 and its downstream antioxidative stress genes, NQO-1 and AKR1C1." (PMID 22325485, 2012).
Lipedema (6 papers, 2020 to 2026). Disorder of adipose tissue characterized by symmetric and bilateral enlargement of the lower extremities due to abnormal deposition of subcutaneous fat often in obese women. "A significant genetic component has been proposed by identifying a missense variant in the AKR1C1 gene (encoding an aldo–keto reductase that catalyzes progesterone inactivation) in a family with autosomal dominant non-syndromic lipedema." (PMID 41575573, 2026). "Alterations in the function of structural protein, such as CAV1 dysfunction, and genetic factors, such as mutations in AKR1C1, further point toward a hormone-sensitive and possibly inherited component in lipedema." (PMID 41575573, 2026). "Recently a mutation in AKR1C1 was found to be associated with lipedema, a disease of subcutaneous fat accumulation." (PMID 36768194, 2023). "Overall, our results suggest that AKR1C1 is the first candidate gene associated with nonsyndromic lipedema." (PMID 32872468, 2020). "Collectively, mutations in AKR1C1 may be able to promote lipedema through progesterone, androgen, or prostaglandin pathways." (PMID 36768194, 2023). "A recent genetic study identifying a mutation in Akr1c1 in a family with lipedema speculated that the analgesic activity of allopregnanolone may play a role in lipedema-associated pain." (PMID 36142221, 2022). "A 638 T > A transversion that results in a one amino acid substitution of L213 to Q in AKR1C1 was identified in a family with three members afflicted by sex-limited autosomal dominant nonsyndromic lipedema." (PMID 36768194, 2023). "The exact genes responsible for the hereditary nature of lipedema are still unknown, however recent research has identified a possible gene connected to lipedema occurrence-AKR1C1." (PMID 40611043, 2025). "Therefore, mutation of AKR1C1 would reduce DHT inactivation, allowing it to promote lipedema through androgen receptor signaling." (PMID 36768194, 2023). "Our results are consistent with AKR1C1 being the first candidate gene for lipedema." (PMID 32872468, 2020). "With our study, we argue in favor of the involvement of AKR1C1 in lipedema." (PMID 32872468, 2020). "To date, AKR1C1 has not been implicated in any genetic condition characterized by or including lipedema among its clinical manifestations." (PMID 32872468, 2020). "Despite the rearrangement of the interaction network of residue 213, MD simulations suggest that the lipedema-associated variant does not dramatically affect the three-dimensional structure of AKR1C1." (PMID 32872468, 2020).
melanoma (6 papers, 2019 to 2025). A malignant, usually aggressive tumor composed of atypical, neoplastic melanocytes. "Our study thus identifies a new potential therapeutic strategy to efficiently kill melanoma cells based on pro-ferroptosis drugs coupled to AKR1C1 ÷ 3 inhibitors." (PMID 31780644, 2019). "Collectively these results show that AKR1C1 ÷ 3 gene expression upregulation and enzymatic activity are responsible for inhibited ferroptosis execution in resistant melanoma cells and that the activity of each individual enzyme seems to be equally required." (PMID 31780644, 2019). "Recent studies suggested that aldo-keto reductases (AKRs), a superfamily of NADPH-linked oxidoreductases, including AKR1C1, AKR1C2, and AKR1C3, are potential NFE2L2 target genes responsible for ferroptosis resistance via inhibiting lipid peroxidation in melanoma cells." (PMID 34938739, 2021). "Our above results showing AKR1C1 ÷ 3 enzymatic activity resulting in ferroptosis execution inhibition imply that lipid peroxides production are crucial executioners of the ferroptotic cell death program also in melanoma cells." (PMID 31780644, 2019). "In ferroptosis resistant melanoma cells, CHAC1 was shown to be upregulated by NRF2 independent from ER stress signaling alongside the Aldo-Keto Reductase Family 1 Member C1 (AKR1C1) capable of degrading lipid radicals." (PMID 41488051, 2025). "Since we previously demonstrated that AKRs expression is under the control of NRF2, in melanoma, and that this TF is actively induced during MO3.13 maturation, we verified the that NRF2 regulates the expression of AKR1C1 also in mature MO3.13." (PMID 39671850, 2024).
esophageal cancer (5 papers, 2016 to 2025). A primary or metastatic malignant neoplasm involving the esophagus. "Previous study showed that AKR1C1/C2 were associated with EDHB-induced inhibition of esophageal cancer cell proliferation and this might promote treatment of esophageal cancer using EDHB, a substrate of the enzymes." (PMID 33935718, 2021). "Overexpression of AKR1C1/C2 increased the EDHB-induced inhibition of esophageal cancer cell proliferation." (PMID 26934124, 2016). "The sensitivity of esophageal cancer cells to EDHB was significantly attenuated by the siRNA knockdown of AKR1C1/C2." (PMID 26934124, 2016). "This study utilized an MRM assay to confirm that AKR1C1/C2 are involved in the EDHB-induced inhibition of esophageal cancer cell proliferation." (PMID 26934124, 2016). "Previous research has also shown that EDHB inhibits esophageal cancer cell proliferation by increasing autophagy and apoptosis through NDRG1 and BNIP3 and markedly increases AKR1C1, AKR1C2, and AKR1C3 mRNA expression." (PMID 26934124, 2016). "AKR1C1/C2 facilitated the induction of early autophagy and late apoptosis by BNIP3 and NDRG1 in ESCC cells after EDHB treatment, thereby promoting the EDHB-induced inhibition of esophageal cancer cell proliferation." (PMID 26934124, 2016). "EDHB was used as a substrate of AKR1C1/C2, and KYSE 180 cells overexpressing AKR1C1/C2 were more sensitive to EDHB, which potentially provides guidance for the use of EDHB for the treatment of esophageal cancer." (PMID 26934124, 2016). "In summary, our observations indicated that AKR1C1/C2 promoted the inhibition of cell proliferation through either EDHB metabolism or BNIP3 and NDRG1 expression and induced early autophagy and late apoptosis in esophageal cancer cells." (PMID 26934124, 2016).
liver cancer (5 papers, 2020 to 2023). An epithelial or non-epithelial malignant neoplasm that arises from the liver. "Other genes in this family (AKR1C1-3) have been associated with different cancers including liver cancer; however the role of AKR1C4 in liver cancer is still unclear as expression level difference between tumor and normal tissue were found to be inconsistent across different databases." (PMID 36503519, 2022). "Accumulating evidence indicates that AKR1C1 is an essential regulator in various cancers, including liver cancer, prostate cancer, and breast cancer." (PMID 34938341, 2021). "Poorer survival rate was observed in those cancer patients with high expression of AKR1C1–3, suggesting that they may serve as prognostic markers for liver cancer." (PMID 37427784, 2023). "Furthermore, a bioinformatic analysis showed elevated AKR1C1–3 expression in liver cancer samples compared with normal liver samples." (PMID 37427784, 2023). "We also identified a proliferative cluster, which mainly consisted of proliferating T cells and a large cluster of HCC cancer cells (40%) expressing both genes associated with normal liver function (ALB, HP, FGA, FGB) and liver cancer (AFP, SPINK1, GPC3, AKR1C1)." (PMID 38030622, 2023).
lung adenocarcinoma (5 papers, 2007 to 2025). A carcinoma that arises from the lung and is characterized by the presence of malignant glandular epithelial cells. "Concurrent loss-of-function mutations in STK11 and KEAP1 in lung adenocarcinoma result in significantly elevated expression of ferroptosis-protective genes, such as AKR1C1/2/3, and resistance to pharmacologically induced ferroptosis." (PMID 38698462, 2024). "Additionally, the NEAT1_1/miR-338-3p/AKR1C1 pathway is implicated in gefitinib resistance in EGFR-mutated lung adenocarcinoma, where increased AKR1C1 expression enhances defense against ferroptosis." (PMID 40078365, 2025). "The expression of AKR1C1, AKR1C2, AKR1C3, and AKR1C4 proteins, which was mainly overexpressed in lung adenocarcinoma (A549) cells and associated with drug resistance in NSCLC, was found in the A549 CD166 + EpCAM + CSC subpopulation." (PMID 33670440, 2021). "In the present study, we found some genes that are related to drug resistance, such as AKR1C1/C2 and NR0B1, or cancer metastasis, such as TM4SF1, were up-regulated in SP cells of human lung adenocarcinoma A549 cell line." (PMID 18034892, 2007).
glioblastoma (4 papers, 2014 to 2026). The most malignant astrocytic tumor (WHO grade IV). "Temozolomide treatment significantly increased the expression of AKR1C1 in U373 and T98G glioblastoma cells." (PMID 25182732, 2014).
hepatocellular carcinoma (4 papers, 2013 to 2025). A malignant tumor that arises from hepatocytes. "HBx can up-regulate the expression of AKR1C1 in the H7402-X cell line, a stable hepatocellular carcinoma cell line with HBV X gene integration." (PMID 24003325, 2013).
lymph node metastasis (4 papers, 2019 to 2025). "The proportion of AKR1C1-positive patients tended toward larger tumor size (≥3 cm) (P = 0.003) and higher risk of lymph node metastasis (P = 0.03)." (PMID 39478199, 2025). "Overall, AKR1C1 was overexpressed in 69.4% (34/49) cases, and the high expression of AKR1C1 is related to regional lymph node metastasis and nerve invasion." (PMID 34127944, 2021). "AKR1C1 is correlated to HPV p16 expression, lymph node metastasis by hematoxylin and eosin stain, SCC histologic grade and smoking history of the patient." (PMID 31182137, 2019).
pancreatic cancer (4 papers, 2011 to 2025). "A similar increased level of Nrf2 and AKR1C1 expression has been reported in pancreatic cancer and such elevation may be associated with resistance to chemotherapeutic intervention." (PMID 26824415, 2016). "Keap1, Nrf2 and the Nrf2 target genes AKR1c1 and GCLC were detected in a panel of five pancreatic cancer cell lines." (PMID 21489257, 2011). "Indeed, knockdown of NUPR1 triggers the expression of lipid detoxification genes such as aldo-keto reductase family 1 member C1 (AKR1C1) in keratinocytes and pancreatic cancer cells but does not affect NRF2 expression or nuclear translocation." (PMID 34359572, 2021).
thyroid cancer (4 papers, 2007 to 2023). "Among the eight ferroptosis-related genes, we selected AKR1C1 to validate its function in thyroid cancer." (PMID 33928101, 2021). "Meanwhile, AKR1C1, HMGCR, TFRC, SQLE, and PGD were risk factors for thyroid cancer prognosis." (PMID 33928101, 2021). "Our data suggested that AKR1C1 (p < 0.0001), DPP4 (p < 0.0001), GPX4 (p = 0.0001), GSS (p < 0.0001), HMGCR (p < 0.0001), TFRC (p < 0.0001), SQLE (p = 0.0004), and PGD (p = 0.0005) were all significantly highly expressed in thyroid cancer tissues compared to normal tissues." (PMID 33928101, 2021). "Moreover, AKR1C1 was suggested as a marker of stem-like cells in thyroid cancer cell lines, though it was not proved by the authors." (PMID 18034892, 2007).
Breast Tumors (3 papers, 2014 to 2024). "In a study led by Zhuo and colleagues, FAA significantly downregulated the expression of both AKR1C1 and AKR1C3 in murine metastatic breast tumor cells (4T1/luc) and human HCC cells (HepG2), indicating a lack of selectivity over AKR1C1." (PMID 38523637, 2024). "Furthermore, a high expression of AKR1C1, but not of AKR1C2 had a negative prognostic value in patients with HER2+ early stage breast tumors." (PMID 37469415, 2023).
cholangiocarcinoma (3 papers, 2021 to 2025). A carcinoma that arises from the intrahepatic biliary tree (intrahepatic cholangiocarcinoma) or from the junction, or adjacent to the junction, of the right and left hepatic ducts (hilar cholangiocarcinoma). "As AKR1C1 is recently shown to be involved in human cholangiocarcinoma, we chose it for further investigation." (PMID 39478199, 2025). "In summary, our findings showed the great importance of FoxM1/AKR1C1 signaling pathway in human cholangiocarcinoma." (PMID 34127944, 2021).
glioma (3 papers, 2021 to 2023). A benign or malignant brain and spinal cord tumor that arises from glial cells (astrocytes, oligodendrocytes, ependymal cells). "Since the enzymes responsible for the metabolization of oxcarbazepine (AKR1C1, AKR1C2, AKR1C3, and AKR1C4) are highly expressed in hepatocytes but not in glioma cells, we expect only marginal transformation to MHD in our in vitro proliferation assay." (PMID 37190109, 2023). "Several aldo-keto reductases are responsible for the metabolization of oxcarbazepine (AKR1C1, AKR1C2, AKR1C3, and AKR1C4), which have not been found to be expressed in the brain or in gliomas." (PMID 37190109, 2023).
Obesity (3 papers, 2020 to 2025). Accumulation of substantial excess body fat. "Overall, our results are the first to draw a link between AKR1C1 expression in pregnant human myometrium, obesity and fetal gender." (PMID 36765000, 2023). "Involvement of AKR1C1 in pregnancy complications related to obesity, and potentially preterm birth, are indicated by our data and warrant further studies." (PMID 36765000, 2023). "Unfortunately, the study did not examine preterm birth rates on the basis of fetal sex, meaning the link between preterm birth and obesity was not specifically associated with the delivery of female babies, as per our linkage of obesity to myometrial AKR1C1 expression." (PMID 36765000, 2023). "Interestingly, AKR1C1 expression was also higher in subcutaneous fat of women with obesity, showing its implication in metabolic disorders." (PMID 32872468, 2020).
prostate tumors (3 papers, 2015 to 2023). "The most recent study on this topic showed that prostate tumor samples with activated AKR1C1, an androgen-metabolizing enzyme, harbor high Sp1 and c-FLIP expression and low AKR1C1, ERβ and Sp3 expression." (PMID 26934124, 2016). "Data presented here shows (i) expression of AKR1C1 decreases in human prostate tumors, (ii) 5α-DHT enhances AKR1C1 expression; (iii) both 3β-Adiol and ERβ suppress c-FLIP activation in DU145 and PC-3 cells but not in LNCaP cells." (PMID 25816367, 2015). "Expression of Sp1 and c-FLIP are elevated while AKR1C1, ERβ and Sp3 are significantly low in human prostate tumor samples." (PMID 25816367, 2015). "Furthermore, in silico analysis revealed significantly decreased expression of both AKR1C1 and ERβ in human prostate tumors compared to normal tissue." (PMID 25816367, 2015). "We also compared the expression of AKR1C1, c-FLIP, Sp1, Sp3 and ERβ in human prostate tumors and normal tissue from oncomine, cancer-profiling database." (PMID 25816367, 2015). "The Aldo-Keto reductase family members (AKR1C1, AKR1C3, AKR1C4, and AKR1C8P) AKR1C1 and AKR1C3 were among the highest upregulated genes in our OC2 network, and their expression increases with disease progression in prostate tumors (left)." (PMID 37484909, 2023).
small cell lung carcinoma (3 papers, 2020 to 2025). Small cell lung cancer (SCLC) is a highly aggressive malignant neoplasm, accounting for 10-15% of lung cancer cases, characterized byrapid growth, and early metastasis. "It has been shown that high expression of AKR1C1 can promote proliferation and migration of small cell lung cancer cells, and it may represent an independent biomarker for assessing the main prognosis and treatment of small cell lung cancer." (PMID 34702254, 2021).
chorioamnionitis (2 papers, 2023 to 2024). A morphologic finding indicating inflammation of the fetal sac membranes. "Among preterm laboring deliveries, clinically diagnosed chorioamnionitis was associated with significantly elevated AKR1C1 expression." (PMID 36765000, 2023). "Initial results indicate an association between chorioamnionitis and myometrial AKR1C1 expression." (PMID 36765000, 2023). "Combined with our data, these findings suggest that NF-кB and AP-1 likely drive AKR1C1 expression during chorioamnionitis-driven preterm birth." (PMID 36765000, 2023). "Upregulated AKR1C1 expression in the myometrium at preterm in-labor with clinical chorioamnionitis suggests that increased 20α-HSD activity is a mechanism through which inflammation drives progesterone withdrawal in preterm labor." (PMID 36765000, 2023). "In spontaneous preterm labor, however, we previously found no increase in AKR1C1 mRNA level in the myometrium except for preterm labor associated with clinical chorioamnionitis." (PMID 37648943, 2024).
Depression (2 papers, 2015 to 2025). "Following the analysis of the metabolic pathways, seven genes including ALOX5, LTA4H, CYP4Y, PLA2G2C, AKR1C1, AKR1D1 and CYP17A1 were employed to elucidate further the potential mechanisms underlying CS treatment of depression." (PMID 40370520, 2025).
esophageal squamous cell carcinoma (2 papers, 2016). Esophageal squamous cell carcinoma (ESCC) is a type of esophageal carcinoma (EC) that can affect any part of the esophagus, but is usually located in the upper or middle third. "Here, we demonstrated that AKR1C1/C2 increased the metabolism of ethyl-3,4-dihydroxybenzoate (EDHB) in esophageal squamous cell carcinoma (ESCC) cells." (PMID 26934124, 2016). "Recent advances in the molecular biology of esophageal squamous cell carcinoma (ESCC) have shown that in ESCC patients, high AKR1C1 expression increase the sensitive of ESCC cells to ethyl-3,4-dihydroxybenzoate (EDHB) providing potential guidance for the chemoprevention of ESCC." (PMID 27188717, 2016).
gastric adenocarcinoma (2 papers, 2022 to 2023). "Interestingly, survival analysis for incidences of stomach adenocarcinoma from TCGA data accessed by the cBioPortal indicated that patients who experienced an overexpression of AKR1C1 and 1C3 were associated with lower survival rates." (PMID 36292923, 2022). "Additionally, the survival analysis data obtained from the online cBioPortal were used to evaluate the prognostic significance of AKR1C1 and AKR1C3 mRNA expression levels in stomach adenocarcinoma tissue samples obtained from The Cancer Genomic Atlas (TCGA) Pan-Cancer Atlas data." (PMID 36292923, 2022).
kidney cancer (2 papers, 2021 to 2022). Primary or metastatic malignant neoplasm involving the kidney. "Upregulation of genes associated with other diseases, renal dysfunction or cancer was also observed, such as Fras1 (Fraser syndrome 1), Cyp21a1 (congenital adrenal hyperplasia), Dbh (associated with kidney dysfunction), and Akr1c1/Myt1/Myf6/Scg2 (kidney cancer)." (PMID 36130284, 2022).